BMP2 (bone morphogenetic protein 2)
Diseases named in the same sentence as BMP2 in open-access papers (continued):
Sharing a sentence is not in itself a finding about the gene and the disease.
osteonecrosis (16 papers, 2012 to 2024). A none disease characterized by death of bone tissue due to a lack of blood supply. "It was concluded that the synergistic effects of LIPUS and BMP-2 delivery can reduce the side effects of osteonecrosis." (PMID 34945337, 2021). "Recently, studies have been conducted on the use of bone morphogenetic protein-2 (BMP-2) in the treatment of osteonecrosis and its role in bone remodeling." (PMID 28936298, 2017). "In addition, SW on bone increased the levels of serum and tissue BMP2 in the treatment of osteonecrosis of the femur head in patients and in animal studies to improve bone remodeling." (PMID 33333838, 2020). "In another steroid-induced osteonecrosis model, bone morphogenetic protein-2 (BMP-2)-loaded poly-L-lactic acid/polylactic-co-glycolic acid/poly-ε-caprolactone (PLLA/PLGA/PCL) composite scaffolds stimulated by LIPUS could facilitate osteoblast differentiation, vascularization, and bone formation." (PMID 37888169, 2023). "The current studies displayed that sole decompression operation did not reverse the process of the steroid-induced osteonecrosis of femoral head, and not alter the pathological changes caused by the local decreased BMP-2 and progressively increased PPAR-γ expression." (PMID 22876776, 2012). "The involvement of NO pathway in SW osteogenic effect was previously reported in vitro, evidencing an increase in Bmp2 and RUNX2 transcription in marrow stromal cells of hips with osteonecrosis." (PMID 28158228, 2017). "The purpose of this study was to compare the clinical outcomes of impacted bone graft with or without recombinant human bone morphogenetic protein-2 (rhBMP-2) for osteonecrosis of the femoral head (ONFH)." (PMID 24956102, 2014). "The expression of BMP-2 in the osteonecrosis femoral head with or without decompression was significantly lower than that in normal animals." (PMID 22876776, 2012).
glioblastoma (15 papers, 2009 to 2025). The most malignant astrocytic tumor (WHO grade IV). "BMP2 signal transduction is therefore considered as a potential therapeutic target for glioblastoma because BMP2 can induce differentiation and apoptosis of tumor cells." (PMID 33116227, 2020). "LncRNA H19 enhances TMZ resistance in glioblastoma through competitive RNA targeting of BMP2." (PMID 40297808, 2025). "Pistollato and colleagues showed that FKBP38 activity is inhibited by BMP2 in glioblastoma cells." (PMID 30314361, 2018). "Thus, elevated FKBP38 levels are associated with increased HIF-1α activity and tumor progression in glioblastoma as part of mechanisms that de-sensitize cancer cells to pro-differentiating BMP2 signals." (PMID 30314361, 2018). "Similarly, a recent study showed that BMP2 can sensitize glioblastoma-stem-like cells to TMZ (500 μM) by downregulating both hypoxia-inducible factor-1α (HIF-1α) and MGMT." (PMID 26546412, 2015). "BMP2, a member of TGFβ superfamily that has been shown to promote GABAergic neuron differentiation, was also downregulated in the TGFβ strong response glioblastomas (Fold change -2.43, p < 0.0013)." (PMID 19192267, 2009). "BMP2 and BMP4, which bind to the same receptor BMPR1, were shown to induce differentiation of glioblastoma-initiating cells." (PMID 24052948, 2013). "Our findings suggest that BMP2 signaling in glioblastoma does not follow a unidirectional paradigm but may exhibit dual or paradoxical roles depending on molecular subtype, tumor microenvironment, and differentiation status." (PMID 40869118, 2025). "BMP2 and BMP4 have been identified as key inhibitors of CSC self-renewal and drivers of CSC differentiation, for example in glioblastoma (GBM) stem cells." (PMID 40277903, 2025).
lung adenocarcinoma (14 papers, 2010 to 2026). A carcinoma that arises from the lung and is characterized by the presence of malignant glandular epithelial cells. "A prior study demonstrated that lung adenocarcinoma cells located near the ossification site produced bone morphogenetic protein-2 and osteopontin, which typically promote and enhance bone growth." (PMID 39932915, 2025). "The study unequivocally showed, through the use of an in vivo orthotopic mouse model, that BMP2 actively enhances the spread of lung adenocarcinoma to other parts of the body." (PMID 40136410, 2025). "Recombinant human BMP2 (rhBMP2) significantly increased the migration and invasion abilities of lung adenocarcinoma cells, and the BMPR inhibitor LDN193189 decreased migration and invasion abilities." (PMID 36175474, 2022). "Although several lines of evidence suggest that BMP2 promotes cell migration and invasiveness in vitro, the in vivo role of BMP2 in the metastasis of lung adenocarcinoma cells remains less well understood." (PMID 36175474, 2022). "Here, we revealed that BMP2 is highly overexpressed in lung adenocarcinoma patients with lymph node metastasis compared with patients without lymph node metastasis." (PMID 36175474, 2022). "Using an in vivo orthotopic mouse model, we clearly demonstrated that BMP2 promotes lung adenocarcinoma metastasis." (PMID 36175474, 2022). "The activation of BMP2 signalling is also found to enhance cell proliferation, migration, invasion and lung metastases of lung adenocarcinoma." (PMID 32750747, 2020). "The gene expression pattern induced by BMP2 in lung fibroblasts significantly correlated with the prognosis of patients with stage I lung adenocarcinomas." (PMID 25924783, 2015). "Knockdown experiments of BMP2 in A549 lung adenocarcinoma cells had shown decreased growth and invasion potential by changes in the tumor cells gene expression pattern revealing therapeutic targets and strategies." (PMID 25924783, 2015). "BMP-2 knockdown by adenovirus inhibited growth and invasion of human lung adenocarcinoma cells by blocking PI3K/AKT signaling." (PMID 24946687, 2014). "Our results indicate that BMP2 promotes EMT in lung adenocarcinoma cells." (PMID 36175474, 2022). "To test whether BMP2 promotes lung adenocarcinoma mobility through the epithelial-to-mesenchymal transition (EMT), we depleted the expression of BMP2 using lentiviral-mediated shRNA delivery to CL1-5 and AS2 cells." (PMID 36175474, 2022). "Previous study indicated that the expression pattern induced by BMP2 in lung fibroblasts may predicts patients’ prognosis in lung adenocarcinoma." (PMID 33005178, 2020). "The gene expression pattern induced by BMP2 in primary lung fibroblasts may predict outcomes of patients with lung adenocarcinomas." (PMID 25924783, 2015). "In pancreatic ductal adenocarcinoma, NBL1 inhibits tumor growth by antagonizing bone morphogenetic protein 2/4 (BMP2/4) signaling and suppressing EMT, whereas in lung adenocarcinoma, NBL1 acts as a transcriptional target of miR-1301-3p to suppress metastasis." (PMID 41158754, 2026). "We screened and verified four differentially expressed BMPs (BMP2, BMP5, BMP6, and GDF10) and one BMPR (ACVRL1), which all were downregulated in lung adenocarcinoma tissues." (PMID 34745928, 2021). "Importantly, we also demonstrate that the BMP2 gene signature identified in the lung fibroblasts in vitro has significant prognostic relevance in human lung adenocarcinomas and may thus serve as novel prognostic cancer markers and therapeutic targets in future." (PMID 25924783, 2015). "However, BMP2, SELP, and SLC6A4 were significantly down-regulated in lung adenocarcinoma cells compared with NHBE cells." (PMID 36147496, 2022). "BMP2, BMP5, BMP6, GDF10, and ACVRL1 were verified as downregulated in lung adenocarcinoma." (PMID 34745928, 2021).
pancreatic cancer (14 papers, 2007 to 2025). "Loss of tumor suppressor WWOX accelerates pancreatic cancer development through promotion of TGFβ/BMP2 signaling." (PMID 40952239, 2025). "Their experiments further concluded that BMP2 directly drives the growth and migration of pancreatic cancer cells and, in vivo, upregulation of miR-211-5p reduces tumor development." (PMID 40867554, 2025). "This study suggests that the relationship between miR-211-5p and BMP2 can be used as a prognostic marker for patients with pancreatic cancer." (PMID 40867554, 2025). "Our research results indicate that the inhibitory effect of pancreatic cancer cell proliferative and metastatic is significantly influenced through miR-211-5p, which interacts with BMP2." (PMID 38059889, 2023). "It has been demonstrated that some BMPs components, such as BMP2, are upregulated in pancreatic cancer patients compared to normal pancreatic tissue." (PMID 36572673, 2022). "Irrespectively, our results show that cancer and/or stromal cells-derived factors like TGF-β1 and BMP2 have the capacity to modulate Runx2 expression in pancreatic cancer and stellate cells in an autocrine/paracrine fashion." (PMID 17876328, 2007). "Additionally, BMP2 expression is increased in pancreatic cancer and has variable mitogenic effects on pancreatic cancer cell lines, with a greater capacity to stimulate growth in cell lines with SMAD mutations." (PMID 38500662, 2024). "The PI3K/AKT pathway, a major cascade-promoting cell migration and invasion, could be activated by BMP-2 in gastric and pancreatic cancer cells, which can dramatically enhance the phosphorylation level of AKT protein." (PMID 27661009, 2016). "Further studies have shown how miR-211 regulates TGF-β-related molecules such as bone morphogenetic protein 2 (BMP2), for example in the context of miR-211-5p expression and pancreatic cancer severity." (PMID 40867554, 2025). "For instance, BMP4- and BMP2- induced MSX2 expression stimulated EMT in pancreatic cancer and cardiac cushion cells, respectively." (PMID 21730974, 2011). "Aspc-1, Capan-1, Panc-1 and T3M4 pancreatic cancer cells were treated with recombinant TGF-β1, BMP2, FGF2, Shh, Ihh and TNF-α for 48 h." (PMID 18163903, 2007). "To further explore their correlation in clinical specimens, we evaluated the expression levels of BMP2 in 58 sets of tumor and non-tumor pancreatic cancer tissues." (PMID 38059889, 2023). "Furthermore, BMP-2-induced phosphorylation of SMAD2/3 promotes epithelial-mesenchymal transition (EMT) and induced cell invasion and migration in breast and pancreatic cancer cells." (PMID 27661009, 2016).
type 2 diabetes (13 papers, 2015 to 2025). "We also measured plasma levels of BMP2 in the 6-week diabetic db/db−/− mouse model of type 2 diabetes in which there was significant increase (428 ± 37 versus 359 ± 40 pg/ml in control)." (PMID 33584642, 2020). "Elevated BMP2 serum concentrations have been reported in patients with type 2 diabetes and moderate obesity." (PMID 31324879, 2019). "Clinically, serum BMP2 has been correlated with plaque burden and coronary artery calcification in patients with type 2 diabetes." (PMID 29596467, 2018). "Of the predicted upstream regulators of the DEGs, CREB1, ERB2 and BMP2 were activated, as was the pathway that is modulated by the anti-Type 2 Diabetes pharmaceutical agent Troglitazone." (PMID 26987907, 2016). "Thus, we investigated the valvular expression of NF-κB, BMP-2 and components of the blood coagulation system in individuals with AS and concomitant type 2 diabetes." (PMID 34494136, 2021). "In addition, BMP-2 levels were significantly increased in patients with type 2 diabetes (T2DM)." (PMID 36909186, 2023). "Also, higher levels of tumor necrosis factor (TNF)- α, as found in type 2 diabetes, may induce NFκB and bone morphogenetic protein-2, both involved in PiT-1 upregulation." (PMID 35477475, 2022). "We investigated whether type 2 diabetes concomitant to aortic stenosis (AS) enhances valvular inflammation and coagulation activation via upregulated expression of NF-κB, with subsequent increased expression of bone morphogenetic protein 2 (BMP-2)." (PMID 34494136, 2021).
liver fibrosis (11 papers, 2017 to 2025). "Apart from renal cells, BMP2 has also been reported to participate in recovery from hepatic fibrosis in mouse models and human liver tissue microarrays, and it can inhibit the formation of the ECM induced by TGFβ signaling in pancreatic stellate cells." (PMID 38132468, 2023). "Moreover, a study from 2018 demonstrated that BMP2 performs an inhibitory effect on hepatic fibrosis through the inhibition of TGF-β1/Smad3 pathways, hepatic stellate cells (HSCs) activation, and epithelial-to-mesenchymal transition (EMT) suppression." (PMID 41157574, 2025). "Notably, adenovirus-mediated delivery of the BMP2 genehas been effective in reducing liver fibrosis and biliary injury in mice.Mechanistically, BMP2 inhibits the proliferation and migration of hepaticstellate cells by counteracting TGFβ signaling and the EMT." (PMID 39484128, 2024). "Bmp2 was also shown to decrease renal interstitial fibrosis and liver fibrosis." (PMID 36805334, 2023). "However, others indicated that BMP-2 restoration might assist in recovery from liver fibrosis by attenuating TGF-β1 signaling." (PMID 40304568, 2025). "For example, we recently reported upregulation of BMP9 expression in HSC and determined its fibrogenic role in the chronic CCl4 mouse liver fibrosis model as well as in human patients with CLD, whereas BMP2 was proven to have antifibrotic effects in CCl4 and BDL models of liver fibrosis." (PMID 31718044, 2019).
Osteopenia (11 papers, 2016 to 2025). Osteopenia is a term to define bone density that is not normal but also not as low as osteoporosis. "The present study shows that combined delivery of HA and low-dose BMP-2 (1 μg) or GDF-5 (5 μg) is highly suitable for the therapy of lumbar osteopenia in aged sheep, including long-term augmentation of bone structure and bone formation, as well as biomechanical stabilization." (PMID 35203721, 2022). "However, they might be inflated by patient selection (only one smoker and one patient with osteopenia) and using BMP-2 in all cages." (PMID 33391920, 2021). "Here, the results showed that LA inhibited oxidative stress, suppressed apoptosis and improved osteopenia by promoting the expression of osteogenesis markers, including ALP, COL-I, OCN, BMP-2, RUNX2 and OSX." (PMID 28611356, 2017). "Our results demonstrate the difference of local BMP2 and ZOL application in regulating bone quality in rabbits with osteopenia, which have significant clinical implications for reducing the risks of osteoporotic fractures." (PMID 27329730, 2016). "This suggests that a BMP-2 dose of ~250 μg may be sufficient for long-term induction of bone formation in the present system, close to the 100 μg recommended for BMP-2, GDF-5 and its mutant BB-1 in the sheep defect model of lumbar osteopenia." (PMID 37378714, 2023).
liver cancer (10 papers, 2014 to 2024). An epithelial or non-epithelial malignant neoplasm that arises from the liver. "Furthermore, from the public clinical microarray database of TCGA, we found that the expression of BMP2 in liver cancer tissues was associated with Arg1 and IL6, the activation marker of MDSCs." (PMID 32195173, 2020). "The overexpression of miR-574-5p downregulates Bone morphogenetic protein 2 (BMP2) facilitating osteoclast differentiation and inducing bone metastasis of liver primary cancer (blue arrow)." (PMID 37958352, 2023). "In this study, the roles that BMP2 played in liver cancer growth were further confirmed and the detailed mechanisms about how BMP2 enhanced the liver cancer growth were also elucidated." (PMID 32195173, 2020). "We analyzed the public clinical database of Roessler Liver, KM plotter, and TCGA, and found that high BMP2 expression indicated poor prognosis of human liver cancer." (PMID 32195173, 2020). "We demonstrated that implantation of rhBMP2 collagen gels promoted the activation of BMP2 signaling in MDSCs and the infiltration of MDSCs into liver cancer tissues of ICR mice." (PMID 32195173, 2020). "In this study, the roles that BMP2 played in liver cancer growth were further confirmed and the detailed mechanisms about how BMP2 enhanced liver cancer growth were also elucidated." (PMID 32195173, 2020). "In particular, the roles that BMP2 play in the development of liver cancer remained controversial, and mechanisms were unclear." (PMID 32195173, 2020). "Notably, liver-cancer-cell-secreted exosomes promote bone metastasis derived from primary liver cancer facilitating osteoclast differentiation through the miR-574–5p/Bone morphogenetic protein 2 (BMP2) axis." (PMID 37958352, 2023). "In this study, we found that both intravenous delivery and local implantation of BMP2 could enhance the growth of liver cancers in vivo." (PMID 32195173, 2020). "As high BMP2 expression indicated poor prognosis in human liver cancer, we went further to study whether the intravenous delivery of rhBMP2 could promote the growth of liver cancer in mouse models." (PMID 32195173, 2020). "Our findings demonstrated that high levels of BMP2 could enhance liver cancer growth via regulating immune cells in the tumor microenvironment, like MDSCs." (PMID 32195173, 2020). "The results demonstrated that BMP2 inducing MDSCs expansion could enhance liver cancer progression via IL6 in human liver cancer as well." (PMID 32195173, 2020). "Our study indicated that increased concentration of BMP2 within the peripheral blood could enhance liver cancer growth via the activation of MDSCs." (PMID 32195173, 2020). "We found that BMP2 could promote liver cancer growth as well as the expansion of MDSCs in mouse models." (PMID 32195173, 2020). "Functions of BMP2 on the survival of liver cancer cells were still controversial." (PMID 32195173, 2020). "Taken together, these results suggested that high levels of BMP2 could promote the growth progression of liver cancer through the activation of MDSCs." (PMID 32195173, 2020). "Previous reports indicated that liver cancer cells could respond to BMP2 signaling differently under different conditions." (PMID 32195173, 2020). "Therefore, considering the potential tumorigenesis concerns of rhBMP2 used in clinics and the uncertainty of roles that BMP2 played in the progression of liver cancer, we mainly focused on the roles that BMP2 play in liver cancer growth." (PMID 32195173, 2020). "It was reported that BMP Receptor I (BMPRIA) was highly expressed in liver cancer cells, and knockdown of BMP2 in liver cancer cells could suppress the migration and invasion of liver cancer." (PMID 32195173, 2020). "Thus, we focused on analyzing the effects of exogenous BMP2 on the growth of liver cancer and the detailed mechanisms." (PMID 32195173, 2020). "In conclusion, increased concentration of BMP2 within the peripheral blood could promote the growth of liver cancers in vivo." (PMID 32195173, 2020).